TREM2 (triggering receptor expressed on myeloid cells 2)
Diseases named in the same sentence as TREM2 in open-access papers (continued):
Sharing a sentence is not in itself a finding about the gene and the disease.
amyloid (continued). "However, adverse outcomes have been reported with both anti-amyloid and anti-TREM2 antibody therapies in the CNS, including amyloid-related imaging abnormalities." (PMID 41440010, 2025). "Moreover, a study using high-throughput flow cytometry identified a population of senescent microglia expressing high levels of Trem2 in a 7-month-old 5xFAD mouse model of amyloidosis, while Trem2-null mice exhibited a reduced number of senescent microglia." (PMID 40234956, 2025). "TREM2 can function alone or in conjunction with additional molecules, such as apolipoprotein E (APOE), to affect microglial functions in disorders caused by amyloid and tau, as well as inflammation and metabolism." (PMID 39015316, 2024). "However, while microglia behaved similarly to wt microglia, it failed to exhibit an upregulated transcriptomic response to amyloidosis, indicating that TREM2 is necessary for microglia activation in response to amyloid." (PMID 38462606, 2024). "Moreover, the opposite phenotypes observed in TREM2 KO and TREM2 R47H KI mouse models in the presence of amyloid pathology versus tauopathy further implicate the complexity of TREM2 function in AD pathogenesis." (PMID 38462606, 2024). "In an APP/PS1ΔE9 mouse model expressing human APOE3 or APOE4, TREM2-deficiency increased plaque growth in the early stages of amyloidosis with a decreased microglial response, without affecting an overall level of plaque deposition." (PMID 38462606, 2024). "It was suggested that TREM2 may act as a costimulatory molecule that helped sustain microglia during amyloidosis when colony stimulating factor (CSF)-1 levels were reduced." (PMID 38462606, 2024). "Considering that no animal model fully mimics the AD related pathologies and 5xFAD mice merely develop amyloid pathology which recapitulates the very early stage of AD, our current data cannot address how TREM2 p.H157Y affects late-stage AD pathologies including tauopathy and neurodegeneration." (PMID 36721205, 2023). "Loss of Trem2 in an APP/PS1 AD mouse model accelerated amyloidogenesis in early disease pathogenesis, whereas Trem2 deficiency did not affect amyloid load at a later disease stage." (PMID 38017562, 2023). "However, several acceptable themes do seem to prevail and relate to the requisite role of membrane-bound TREM2 in encircling the amyloid plaques thereby altering their morphology to a more compact architecture and an attenuated neuritic pathology." (PMID 37296669, 2023). "When injecting AD-tau into an amyloid-murine model, chronic activation of TREM2 with an activating TREM2 antibody increased amyloid load and tau-phosphorylation, indicating that chronic activation of TREM2 in late-stage AD may exacerbate the disease." (PMID 36981033, 2023). "Our data further suggest that TREM2 may also act upstream of C1q‐mediated microglia‐synapse engulfment in amyloid models, in line with a previous study in a tau model of AD." (PMID 37575021, 2023). "It is therefore tempting to speculate that the HSV1-induced down-regulation of TREM2 might promote or aggravate AD-related pathologies, especially amyloid plaque accumulation." (PMID 37595041, 2023). "Furthermore, in APP23 transgenic mice, microglia surrounding Aβ increased expression of TREM2 corresponding with the progression of amyloid pathology." (PMID 36966244, 2023). "Additionally, TREM2 LOF reduced brain glucose metabolism in aged and amyloid mouse models, implicating TREM2 in regulating brain metabolic activity." (PMID 36635496, 2023). "Next, we explored whether other microglial markers, such as the microglia-associated triggering receptor expressed on myeloid cells (TREM2) and CD68, that may be altered in the presence of amyloid pathology, were affected by DHA treatment." (PMID 36678710, 2022).
amyloid (continued). "Treatment with an anti-TREM2 agonist antibody has been shown to promote microglia activation and induce phagocytosis of amyloid in murine models of β-amyloidosis, reducing the amount of amyloid plaques and neuronal damage." (PMID 36275012, 2022). "TREM2 is also known to orchestrate microglial reactivity during amyloid pathology." (PMID 35746551, 2022). "We demonstrated impaired trafficking of TREM2 to the plasma membrane of erythrocytes in DS, which could affect amyloid clearance from blood cells." (PMID 34209847, 2021). "Functional studies demonstrated that deletion of Trem2 altered amyloid pathology in opposite directions depending on the stage of the disease, but overexpression of TREM2 reduced the pathology in transgenic mouse models of amyloidosis." (PMID 34731000, 2021). "In addition, Trem2 is also upregulated in an amyloidosis progression-related pattern, predominantly in plaque-surrounding microglia." (PMID 33557250, 2021). "However, with the progression of amyloid pathology, the upregulation of Trem2 mitigates inflammatory response, promotes immune tolerance, and facilitates Aβ escape from microglial clearance." (PMID 33557250, 2021). "Therefore, TREM2 insufficiency prevented proliferation and clustering of microglia around amyloid plaques facilitating neurodegenerative diseases." (PMID 33652870, 2021). "For example, previous literature demonstrating increased TREM2 expression in other amyloid mouse models suggests that evaluating additional amyloid mouse models with a TREM2 focus could be a potential next step." (PMID 34658769, 2021). "Consequently, the chronic, antibody-mediated activation of TREM2, as well as TREM2 upregulation, resulted in recruitment of microglia to plaques, decreased amyloid deposition and improvement in spatial learning and novel object recognition memory in AD models." (PMID 34587978, 2021). "We did not observe the downregulation of homeostatic genes in AD groups, and while TREM2, CLEC7A and CTSD were indeed overexpressed in the presence of amyloidosis, only TREM2 and CTSD upregulation seemed to be specific of FAAH deletion in pathological conditions." (PMID 34587978, 2021). "Because amyloid plaque deposition is associated with the accumulation of disease‐associated microglia (DAM), we examined expression of the DAM markers Trem2, Clec7a, and CD45 within the cortex of 5XFAD/RKO compared with the 5XFAD." (PMID 31800167, 2020). "Furthermore, our earlier findings that antibody‐mediated amyloid plaque clearance is TREM2‐dependent open the opportunity of a combinatorial treatment using anti‐Aβ antibodies together with microglia stimulating antibodies such as 4D9." (PMID 32154671, 2020). "Further studies are necessary to investigate whether the IL-4 signaling pathway cross-talk with TREM2 is involved in a protective microglial phenotype in response to amyloid pathology in AD models." (PMID 32959884, 2020). "In the context of the current findings, it is thus possible that a TREM2-related neuroimmune response in ApoE4-carriers attenuates either an amyloid-induced deposition of tau pathology itself or the downstream consequences of tau that ultimately lead to neurodegeneration and cognitive decline." (PMID 33032659, 2020). "Analysis of the 5xFAD mouse, a widely used amyloid pathology model, and three mouse models based on LOAD genetics carrying APOE4 and TREM2*R47H alleles demonstrated overlaps with distinct human AD modules that, in turn, were functionally enriched in key disease-associated pathways." (PMID 33172468, 2020). "In addition to presenting fewer amyloid plaques, the plaques in TREM2‐overexpressing AD mice were more compact and less filamentous and opposite to changes seen in TREM2 KO‐AD mice." (PMID 30740661, 2019). "Whether exaggerated Treml1, which is observed in the Velocigene Trem2−/− mice, is also playing a protective role when crossed to an amyloid model of disease is unknown." (PMID 29040522, 2018).
amyloid (continued). "Results of these studies were controversial, with some stipulating that TREM2 in microglia increase phagocytosis and clearance of Aβ, while others have suggested that disruption of TREM2 reduces amyloid plaque load." (PMID 29311768, 2017). "In addition, TREM2 is strongly expressed in AD brain tissue, notably close to amyloid plaques and can mediate amyloid plaque phagocytosis." (PMID 28674485, 2017). "Furthermore, transgenic amyloid mouse models indicate an age dependent increase of TREM2 mRNA expression in the brain." (PMID 28197095, 2017). "Indeed, lentiviral overexpression of TREM2 reduced pathology and improved cognitive performance in a mouse model of AD-like amyloidosis." (PMID 28303091, 2017). "The impairment of this inducible, miRNA-34a-regulated TREM2- and MG-cell based amyloid clearance mechanism may thereby contribute to the age-related amyloidogenesis associated with both AD and PrD." (PMID 27378912, 2016). "In addition, as the comparative transcriptomics and FACS-qPCR analysis showed, both the pro-inflammatory microglial subgroups (LPS-MDL and IFN-MDL) and the anti-inflammatory microglial subgroup (NEUD-MDL, Trem2-DAM) were significantly activated at the early stage of AD amyloid pathology." (PMID 41348686, 2025). "Therefore, a better understanding of the physiological role of TREM2 in microglia regulation and how TREM2 signaling affects tau aggregation and propagation in an amyloid-dependent and independent manner is required before targeting TREM2 as a therapeutic entry point for AD." (PMID 37371067, 2023). "Thus, in addition to inducing an immune response, wild-type TREM2 may protect against amyloid pathology by the Aβ-induced release of sTREM2, which blocks Aβ aggregation and neurotoxicity." (PMID 33823153, 2021). "Moreover, numerous studies support that TREM2 has critical role on tauopathy and amyloid pathology." (PMID 31800167, 2020). "In addition, the mouse models used to study the effects of TREM2 on amyloid plaque clearance not only highly overexpress APP but also express rather aggressive familial AD‐associated mutations, which may override modulatory effects of TREM2." (PMID 27402340, 2016). "This type of comprehensive studies are crucial to continue disentangling the beneficial (or detrimental) role(s) of TREM2 and CD33, and respective intracellular signalling pathways, in murine models of amyloidosis, tauopathy, or mixed pathologies." (PMID 37580702, 2023). "TREM2 KO/APPPS1 mice exhibit a reduction in inflammation and the accumulation of amyloid and tau, suggesting that TREM2 is involved in AD pathology." (PMID 34074018, 2021). "Another possibility is that Trem2 was induced by multiple factors of neuroinflammation, because it was a Stage 2 DAM marker and upregulated at the late stage of amyloidosis and neuroinflammation." (PMID 33557250, 2021). "Conversely, the observation that deletion of TREM2 in APPPS1-21 mice decreased the Aβ burden in 2-months-old animals but resulted in higher Aβ accumulation in the cortex of 8-months-old animals suggests that MGnD could be beneficial in the later stages of amyloid pathology." (PMID 30572908, 2018). "Since TREM2 is specifically expressed by microglia in the brain, we hypothesized that soluble TREM2 (sTREM2) levels may increase together with in vivo biomarkers of microglial activity and amyloidosis in an AD mouse model as assessed by small animal positron-emission-tomography (μPET)." (PMID 28197095, 2017). "The persistent upregulation of TREM2 and PU.1 expression in 5 × FAD mice may represent a defense response of the innate immune system to counterbalance amyloid plaque accumulation in the AD brain." (PMID 40376093, 2025). "In APP23, 5xFAD, and APPPS1 models with robust amyloid pathology but an absence of tau pathology, TREM2 expression levels are increased in microglia and other myeloid cells surrounding amyloid plaques." (PMID 39219300, 2025).
amyloid (continued). "Studies on TREM2, a receptor thought to contribute to the DAM phenotype, have shown opposing outcomes where its depletion results in improved or worsened disease in PS19 (tauopathy) and 5xFAD (amyloidosis) Alzheimer’s disease (AD) mouse models, respectively." (PMID 38600001, 2024). "That said, single-cell analyses of T cells infiltrating the brain of mice affected by amyloid, tau or combined (amyloid and tau) pathology suggest that T cell reactivity is not influenced by TREM2 expression in the DAM49." (PMID 38594240, 2024). "In transgenic animal models, amyloidosis results in more severe neurodegeneration and greater fibril branching in the absence of TREM2, suggesting a neuroprotective role." (PMID 38093257, 2023). "TREM2 activation of microglia reduces extracellular amyloid plaques and increases the number of microglia surrounding the plaques in multiple mouse AD models, including the APP/PS1 model with lentiviral TREM2 overexpression and the 5xFAD model with microglial TREM2 overexpression." (PMID 34523252, 2021). "Other studies have not revealed obvious phenotypes in young Trem2 R47H expressing mice, or even Trem2 knockout mice, unless they are aged or bred to amyloid mouse models." (PMID 32959884, 2020). "Although TREM2 protein expression is increased in AD, TREM2 protein levels do not correlate with amyloid plaque accumulation." (PMID 32840654, 2020). "Recent important studies have also shown that impaired/absent Trem2 function attenuates the microglial response to amyloid pathology by regulating microglial number around plaques, regulating microglial activity, and restricting neuritic damage." (PMID 32959884, 2020). "Furthermore, our results suggest the effect of Trem2 deletion on Apoe expression is apparent only in APP mice and depends on the amyloid deposition." (PMID 32703241, 2020). "Here we have examined Trem2 effect in an APOE isoform-dependent and amyloid-dependent manner by directly comparing age-matched APP/E3 and APP/E4 mice that are at different stages of amyloid pathology." (PMID 32703241, 2020). "No reduction in amyloid pathology or phagocytosis was detected in the R47H transgenic mice, but this is not unexpected given the variable amyloid changes in TREM2 KO‐AD mice." (PMID 30740661, 2019). "Genetic variants of genes such as CD33 and TREM2 have been shown to alter (increase or decrease) the phagocytic functions of microglia and thus may directly (or indirectly) contribute to tau pathology, independent of their potential effects on amyloid pathology." (PMID 26057852, 2015). "To understand how Trem2 H157Y affects brain transcriptional profiles, we conducted bulk RNA sequencing with brain RNA samples from the non-amyloid-bearing mice at 6 months of age and amyloid-bearing mice at 8.5 months of age." (PMID 36721205, 2023). "The ability of TransComp-R to identify well-known hub genes, such as TREM2 and TYROBP, identified through other computational methods provided a positive confirmation of our modeling methodology, especially given analysis using a traditional amyloid mouse model dataset." (PMID 34658769, 2021). "In the 5xFAD model of amyloidosis, microglia without TREM2 internalized less fibrillar Aβ." (PMID 34587978, 2021). "After antibody binding to Aβ, uptake and amyloid plaque clearance increase in a concentration‐dependent manner in the presence or absence of functional TREM2, although the total uptake capacity of cells lacking TREM2 is reduced." (PMID 27402340, 2016). "Our hypothesis in the current study was that targeting TREM2 with an antibody, thereby activating the receptor, would increase TREM2 function leading to immune modulation, clearance of amyloid deposition, and improved cognition without the need to directly target the Aβ peptide itself." (PMID 32795308, 2020).
Nasu-Hakola disease (125 papers, 2010 to 2026). "Clinical exome sequencing detected a homozygous c.371T>G mutation in the TREM2 gene (exon 2), confirming the diagnosis of Nasu-Hakola disease." (PMID 41510405, 2025). "In Nasu-Hakola disease, TREM2 gene mutations lead to dysfunction in both microglia and osteoclasts, which in turn damage neuronal health and result in cognitive decline." (PMID 40097409, 2025). "Further, loss of function mutations of TREM2 is associated with Nasu-Hakola disease, an inflammatory degenerative disease of the brain and bone, leading to premature dementia and death." (PMID 38836051, 2024). "A complete loss of function of TREM2 or DAP-12 results in Nasu-Hakola disease, a rare inherited leukodystrophy characterized by bone cysts, bone fractures and sclerosing leukoencephalopathy associated with progressive pre-senile dementia." (PMID 36803190, 2023). "Homozygous TREM2 variants are associated with Nasu-Hakola Disease—a form of early-onset dementia—while heterozygous variants are linked to AD." (PMID 38025464, 2023). "Homozygous mutations in either TREM2 or its adapter protein DNAX-activating protein of 12 kDa (DAP12) result in Nasu-Hakola disease (NHD), a progressive neurodegenerative disorder with massive gliosis and demyelination in the subcortical white matter." (PMID 36389767, 2022). "Patients with Nasu-Hakola Disease are homozygous for loss-of-function mutations in either DAP12 or TREM2, and the disease is characterized by presenile dementia and bone cysts." (PMID 36119485, 2022). "Aβ deposits have been observed in the cortex of a 39-year-old woman with the TREM2 Q33X mutation and Nasu-Hakola disease." (PMID 36002854, 2022). "Nasu-Hakola disease (NHD) is an autosomal recessive disorder caused by rare genetic variants in either triggering receptor expressed on myeloid cells 2 (TREM2) or DNAX Adaptor Protein 12 kD (DAP12) genes." (PMID 33568650, 2021). "Homozygous loss-of-function mutations of Trem2 or Tyrobp (Dap12) cause Nasu-Hakola disease accompanied by demyelination and axonal loss." (PMID 33863908, 2021). "The association between TREM2 and cognitive impairment was first identified through the studies examining the mutations in the patients with Nasu-Hakola disease (NHD)." (PMID 34867303, 2021). "Homozygous or compound heterozygous mutations of TREM2 have been associted to Nasu-Hakola disease which is characterized by bone involvement with an early-onset FTD phenotype." (PMID 34248820, 2021). "The relevance of TREM2 in brain functioning is highlighted by recessive mutations in TREM2 causing Nasu Hakola disease, and FTD in some patients." (PMID 33853652, 2021). "The more severe phenotype, which was associated with bone malformation, bears similarity to TREM2-associated Nasu-Hakola disease and suggests CSF-1 and TREM2 act on convergent pathways." (PMID 32430064, 2020). "Previously, it was shown that both plasma and CSF sTREM2 were useful to detect those with homozygous TREM2 mutations (e.g. p.T66 M, p.W198X, p.Q33X and p.Y38C) that lead to Nasu-Hakola disease or an FTD-like syndrome." (PMID 31779670, 2019). "Note that AD is associated with loss of function mutations in only one TREM2 gene, whereas loss-of-function in both TREM2 genes results in a different disease: Nasu-Hakola disease." (PMID 30297984, 2018). "TREM2 variants were originally identified as causative mutations in patients with Nasu-Hakola disease." (PMID 29598827, 2018). "Homozygous TREM2 mutations lead to a rare syndrome called Nasu-Hakola disease, which is associated with an early-onset FTD-like dementia, and homozygous TREM2 variants are associated with FTD-like syndromes without bony involvement." (PMID 30111356, 2018). "Deficiency in TREM2 leads to Nasu-Hakola disease and patients with partial loss-of-function mutations in CSF1R suffer from hereditary diffuse leukoencephalopathy with spheroids (see reviews)." (PMID 29448957, 2018).